UTP6 (UTP6 small subunit processome component)
Description:
Part of the small subunit (SSU) processome, first precursor of the small eukaryotic ribosomal subunit. During the assembly of the SSU processome in the nucleolus, many ribosome biogenesis factors, an RNA chaperone and ribosomal proteins associate with the nascent pre-rRNA and work in concert to generate RNA folding, modifications, rearrangements and cleavage as well as targeted degradation of pre-ribosomal RNA by the RNA exosome. Involved in nucleolar processing of pre-18S ribosomal RNA.
Synonyms: C17orf40; HCA66
Tractability: Small molecule: a structure with a bound ligand is known. PROTAC: ubiquitination databases record sites on it; its protein half-life has been measured.
Gene: Protein-coding gene on chromosome 17 (31,860,904 to 31,901,746, reverse strand). Ensembl gene ENSG00000108651.
Subcellular location: Nucleus, nucleolus
Subcellular location (Human Protein Atlas): Nucleoli; Mitotic chromosome
Pathways (Reactome):
Metabolism of RNA: Major pathway of rRNA processing in the nucleolus and cytosol; rRNA modification in the nucleus and cytosol
Gene Ontology:
Molecular function: protein binding; snoRNA binding
Biological process: ribosomal small subunit biogenesis; maturation of SSU-rRNA; maturation of SSU-rRNA from tricistronic rRNA transcript (SSU-rRNA, 5.8S rRNA, LSU-rRNA); RNA processing
Cellular component: chromosome; nucleolus; small-subunit processome; nucleoplasm; Pwp2p-containing subcomplex of 90S preribosome
Genetic constraint (gnomAD): Loss-of-function variants: 47 observed, 89.14 expected, observed/expected ratio (o/e) 0.53, 90% interval 0.42 to 0.67. The upper end of that interval is the gene's LOEUF score, 0.67, which puts it in group 2 of 6, group 1 being the genes least tolerant of losing a copy. Missense variants: 586 observed, 690.29 expected, observed/expected ratio (o/e) 0.85, 90% interval 0.79 to 0.91. Synonymous variants: 201 observed, 237.57 expected, observed/expected ratio (o/e) 0.85, 90% interval 0.75 to 0.95.
Homologues: Orthologues: chimpanzee UTP6 (99% identical), macaque UTP6 (97% identical), pig UTP6 (88% identical), mouse Utp6 (86% identical), rabbit UTP6 (86% identical), guinea pig UTP6 (86% identical), dog UTP6 (86% identical), rat Utp6 (83% identical), zebrafish utp6 (53% identical), tropical clawed frog utp6 (52% identical), Drosophila melanogaster CG7246 (25% identical).
Diseases named in the same sentence as UTP6 in open-access papers:
UTP6 is named in the same sentence as 13 diseases in open-access papers, as found by Europe PMC text mining. Sharing a sentence is not in itself a finding about the gene and the disease. The quoted sentences say what the papers report.
colorectal cancer (2 papers, 2021 to 2024). A primary or metastatic malignant neoplasm that affects the colon or rectum. "Low expression of the UTP6 was found to be associated with chemoradiotherapy resistance and the prognosis of colorectal cancer possibly via regulating FOXK2 expression by transcription factor pathways." (PMID 34485268, 2021). "Additionally, we identified and validated UTP6 as a new effective predictor for chemoradiotherapy sensitivity and a prognostic factor for the survival of colorectal cancer patients using our data and the GSE35452 dataset." (PMID 34485268, 2021).
breast carcinoma (1 paper, 2024). "UTP6 was enriched in the process of snoRNA binding, while snoRNA activated PARP-1 ADPRylates DDX21 in BRCA1/2-wild-type breast cancer cells to promote enhanced ribosome biogenesis and cell proliferation." (PMID 39095659, 2024). "Six breast cancer differentially localized proteins were got: CCNT1, NSUN5, PRPF4, RECQL4, UTP6, ZNF500." (PMID 39095659, 2024). "Based on the results of survival analysis (p < 0.05), it was found that the results of UTP6, NSUN5 and RECQL4 proteins were more relevant to the prognosis of breast cancer, while the results of CCNT1 and PRPF4 were not." (PMID 39095659, 2024).
colon cancer (1 paper, 2021). "In the present study, we found hypermethylation in colon cancer tissue and the cg10893370 and cg13453082 sites located in the UTP6 promoter in CRC stem cells." (PMID 34485268, 2021).
hepatocellular carcinoma (1 paper, 2024). A malignant tumor that arises from hepatocytes. "UTP6 Small Subunit Processome Component (UTP6), or Hepatocellular carcinoma antigen 66 (HCA66), is a positive regulator of Apaf-1-dependent apoptosis." (PMID 38448973, 2024).
neurofibromatosis type 1 (1 paper, 2017). A clinically heterogeneous, neurocutaneous genetic disorder characterized by cafe-au-lait spots, iris Lisch nodules, axillary and inguinal freckling, and multiple neurofibromas. "Haploinsufficiency-derived UTP6 under-expression in neurofibromatosis type 1 (NF1) cells resulted in those cells being less susceptible to apoptosis." (PMID 28589857, 2017).
prostate carcinoma (1 paper, 2025). A carcinoma that arises from epithelial cells of the prostate gland. "Previous studies have reported that UTP6 participates in pre-18S ribosomal RNA (rRNA) processing within the nucleolus, while HN1, also known as JPT1, regulates cell migration in carcinomas including breast and prostate cancer." (PMID 40917497, 2025).
rectal cancer (1 paper, 2021). A primary or metastatic malignant neoplasm that affects the rectum. "The present study provided insight into the role of UTP6 in CRT-sensitive in rectal cancer patients." (PMID 34485268, 2021). "Unfortunately, the precise mechanism of UTP6 involved in CRT sensitivity in rectal cancer patients is still unclear." (PMID 34485268, 2021). "Moreover, we verified the UTP6 expression in 125 locally advanced rectal cancer (LARC) patients samples by immunohistochemical analysis." (PMID 34485268, 2021). "In addition, we detected the UTP6 expression in the rectal cancer tissues and adjuvant cancer tissues, the result demonstrated that UTP6 expression value was similar in rectal cancer and adjacent cancer tissues (P = 0.571)." (PMID 34485268, 2021). "To validate the hub genes, we examined the expression of UTP6 and FTSJ3 in rectal cancer tissues of CRT-resistant and CRT-sensitive cases in our datasets." (PMID 34485268, 2021). "To validate the hub genes in our data set, we examined the expression level of UTP6 and FTSJ3 by comparing the rectal cancer tissues of CRT-resistant and-sensitive cases using an external dataset." (PMID 34485268, 2021). "The findings suggest that the combination of demethylation therapy targeting UTP6 and cancer stem cells during CRT might be beneficial to rectal cancer patients." (PMID 34485268, 2021).
tumor (6 papers, 2017 to 2025). "Haploinsufficiency of UTP6 seems to reduce cellular apoptosis, increasing the risk of tumor development." (PMID 31652930, 2019). "Somatic loss of the remaining UTP6 allele in tumours of patients with NF1 microdeletions may contribute to malignanttransformation by increasing chromosome instability and aneuploidy." (PMID 28213670, 2017). "In the training dataset, in the high-risk score group a larger tumor size was seen (2.7 ± 1.2 vs. 3.5 ± 1.6, P = 0.002), more lymph nodes were retrieved (11.2 ± 8.7 vs. 15.7 ± 13.8, P = 0.028), and poorer histopathology was observed (P = 0.026) compared with UTP6 low expression group." (PMID 34485268, 2021). "RECQL4, UTP6, CCNT1, and NSUN5 were enriched in the regulation process of cyclin dependent protein kinase activity, Cyclin D1 is one of the effectors of tumor gene Neu and Ras causing malignant transformation of cells in breast cancer." (PMID 39095659, 2024). "Genomic data indicated that UTP6 and HN1 amplification on chromosome 17q were associated with the activations of ribosome biogenesis and cell migration, respectively, which were relevant to tumor proliferation and metastasis." (PMID 40917497, 2025). "In addition to the deletion of SUZ12 and ATAD5, hemizygosity forthe genes COPRS, UTP6 and RNF135 may alsocontribute to the increased tumour risk associated with NF1 microdeletions." (PMID 28213670, 2017). "Univariate analysis revealed that tumor size (P = 0.004), ypTNM stage (P < 0.001), AJCC TRG grade (P = 0.013), UTP6 expression (P < 0.001), CD133 expression (P < 0.001), and the pre-CRT-CA19-9 level (P = 0.012) were independently associated with DFS in LARC patients following CRT and TME." (PMID 34485268, 2021). "Moreover, the amplification of 2 cis-genes, UTP6 and HN1, located at 17q, were found to activate ribosome biogenesis and cell migration in CDC, respectively, further relevant to the more malignant phenotypes, including tumor proliferation and metastasis." (PMID 40917497, 2025).
cancer (4 papers, 2021 to 2025). A tumor composed of atypical neoplastic, often pleomorphic cells that invade other tissues.
UTP6 also shares sentences with these, for which no sentence is quoted: breast tumors (1 paper); esophageal cancer (1); intellectual disabilities (1); migraine (1).